IFNG (interferon gamma)
Diseases named in the same sentence as IFNG in open-access papers (continued):
Sharing a sentence is not in itself a finding about the gene and the disease.
goiter (2 papers, 2009 to 2021). Enlargement of the thyroid gland usually caused by lack of iodine in the diet, hyperthyroidism, or thyroid nodules. "Results showed that the relative expression of MAFTRR and IFNG in the thyroid glands from the HT patients were higher than that from patients with simple goiter." (PMID 34869781, 2021). "We have previously reported that thyr-IFNγ transgenic mice develop primary hypothyroidism (low T4, high TSH, and low iodine uptake), goiter, and growth defect." (PMID 19924240, 2009).
hypoplastic myelodysplasia (2 papers, 2018 to 2019). "In myelodysplasia patients treated with DAC, IFNγ expression by CD4+ T cells was not promoted." (PMID 29850630, 2018).
idiopathic dilated cardiomyopathy (2 papers, 2012 to 2016). Decreased function of the heart associated with cardiac enlargement and congestive heart failure, of unknown cause. "The AA homozygote for IFNG +874T/A polymorphism was associated with adverse outcome, worse prognosis as well as with measures of disease severity in idiopathic dilated cardiomyopathy in a recent study." (PMID 23077565, 2012).
idiopathic inflammatory myopathies (2 papers, 2015 to 2022). "In our in vitro studies, the highest expression of NKG2D ligands was observed under combined IFNγ and TNFα treatment, two cytokines highly abundant in the muscle microenvironment of idiopathic inflammatory myopathies." (PMID 26646698, 2015).
Klebsiella Infections (2 papers, 2017 to 2019). Infections with bacteria of the genus KLEBSIELLA. "The fact that TRIF is required for type I IFN production following Klebsiella infection suggests that the impairment of IFNγ production in TRIF−/–mice is secondary to the deficient type I IFN production in these mice." (PMID 30452654, 2019). "Likewise IFNγ-deficient mice, IL1R−/− mice are exquisitely susceptible to Klebsiella infection demonstrating the importance of IL1β-controlled responses for host survival and bacterial clearance." (PMID 30452654, 2019). "Remarkably, type I IFN signalling is dispensable in myeloid cells including alveolar macrophages, monocytes and neutrophils for host defence and IFNγ activation, uncovering a hitherto unknown crosstalk between alveolar macrophages and NK cells based on type I IFN and IFNγ in Klebsiella infection." (PMID 30452654, 2019).
leiomyoma (2 papers, 2018 to 2023). A well-circumscribed benign smooth muscle neoplasm characterized by the presence of spindle cells with cigar-shaped nuclei, interlacing fascicles, and a whorled pattern. "Leptin induces a tumor-friendly microenvironment through upregulation of pro-inflammatory (IFNγ, IL-8, IL-6, GM-CSF, MCP-1, and TNF-α), fibrotic (TGF-β1, TGF-β2, and TGF-β3), and angiogenic (VEGF-A, HGF, and Follistatin) factors in human leiomyoma cells." (PMID 36771423, 2023). "Our study found that leptin treatment of leiomyoma cells increased pro-inflammatory factors, MCP-1, IFNγ, IL-8, GM-CSF, IL-6, and TNF-a." (PMID 36771423, 2023).
lentivirus infection (2 papers, 2023 to 2025). Virus diseases caused by the Lentivirus genus. "Comparing CAR-T cells that with functional TRAC locus (conventional CAR-T, made by lentivirus infection), IRU CAR-T cells had significantly lower frequency of IFNγ producing cells." (PMID 38123592, 2023).
Leukocytoclastic vasculitis (2 papers, 2016 to 2018). "Leukocytoclastic vasculitis in an individual with interferon-gamma autoantibodies and disseminated M. abscessus has also been reported." (PMID 30453935, 2018).
Listeria meningitis (2 papers, 2019 to 2022). Inflammation of the meninges caused by listeria monocytogenes infection, usually occurring in individuals under the age of 3 years or over the age of 50 years. "We have recently reported its application in fungal diagnosis as well as confirming the first case of listeria meningitis in a patient with autoantibody against interferon gamma and another one with Mycobacterium marinum infection." (PMID 35442979, 2022).
localized scleroderma (2 papers, 2021 to 2024). Localized scleroderma is the skin localized form of scleroderma characterized by fibrosis of the skin causing cutaneous plaques or strips. "Other treatment options such mycophenolate mofetil, cyclosporine, and biologics therapies (abatacept, tocilizumab, interferon gamma) were effective in cases of refractory localized scleroderma en coup de sabre." (PMID 34640533, 2021). "One case report described a patient with localized scleroderma en coup de sabre complicated by orbital involvement who was successfully treated with interferon gamma (100 mg 3 times a week subcutaneously—52 mg/m2 body surface area)." (PMID 34640533, 2021). "Other commonly suggested therapies including mycophenolate mofetil, hydroxychloroquine, abatacept, tocilizumab, cyclosporine, and interferon gamma were used in cases of contraindications methotrexate or intolerance and affected a small number of patients with localized scleroderma en coup de sabre." (PMID 34640533, 2021).
lumbar disc herniation (2 papers, 2020 to 2025). "Interferon gamma has a pronociceptive effect in lumbar disk herniation, as it is released during degeneration by stimulating circulating macrophages at the level of disk tissue and in the bone marrow." (PMID 41303319, 2025). "We investigated the influence of pain decrease after lumbar microdiscectomy on the interferon gamma (IFN-γ) serum level in patients with lumbar disc herniations." (PMID 33110454, 2020).
lupus vulgaris (2 papers, 2024 to 2025). A form of cutaneous tuberculosis. "Lupus vulgaris, while having a similar histology to LMDF, shows positive results for interferon-gamma release in serum and acid-fast Bacillus (AFB) staining in skin biopsies." (PMID 39070463, 2024).
lymphocytic colitis (2 papers, 2014 to 2025). Microscopic colitis characterized by the accumulation of lymphocytes in the colonic epithelium and lamina propria. "Lymphocytic colitis was recently shown to be associated with increased TNFA, IFNG, and PTGER4, and a role for prostaglandin proposed in activating pathogenic lymphocytes." (PMID 24959420, 2014).
malignant uterine neoplasms (2 papers, 2016 to 2025). "Another investigation assessed the impact of intraoperative and postoperative DEX vs. placebo on NK cell function in patients with uterine cancer, revealing increased interferon-gamma (IFN-γ) levels in the DEX group." (PMID 40697508, 2025).
MALT lymphoma (2 papers, 2016 to 2021). An indolent, extranodal type of non-Hodgkin lymphoma composed of small B-lymphocytes (centrocyte-like cells). "CagY predominantly drives Interferon-gamma (IFN-γ) and Interleukin-17 (IL-17) secretion by gastric CD4+ T cells from H. pylori-infected patients with low-grade gastric MALT lymphoma." (PMID 34502367, 2021).
mantle cell lymphoma (2 papers, 2022 to 2023). Mantle cell lymphoma is a rare form of malignant non-Hodgkin lymphoma affecting B lymphocytes in the lymph nodes in a region called the ``mantle zone''. "In mantle cell lymphoma (MCL), HDAC8 inhibition has been observed to increase interferon-gamma (IFNγ)-producing NK cells." (PMID 36231123, 2022).
mastocytoma (2 papers, 2014 to 2024). A localized tumor composed of sheets of mast cells without atypia. "Inspired by these studies on their potential beneficial effects in anti-tumor therapy, we genetically engineered murine mastocytoma line P815 with light-switchable modules (named P815-IFNG) to produce murine IFNG and CXCL10." (PMID 39080467, 2024).
metabolic (2 papers, 2017 to 2023). "Pathway analysis then demonstrated that IL23-mediated signaling events, interferon gamma signaling, natural killer (NK)-κB signaling pathway, chemokine receptors that bind chemokines, GPCR ligand binding, and metabolic disorders of biological oxidation enzyme pathways play important roles in NMO." (PMID 26941100, 2017).
monocytic leukemia (2 papers, 2010 to 2025). "In other studies, IFNG inhibited phagocytosis in macrophages derived from the spleen, peritoneum, and the human monocytic leukemia cell line THP-1." (PMID 40332792, 2025). "LcrV was shown to bind to human U937 monocytic leukemia cells and human alveolar macrophages, provided that human IFNγ was present; in addition, it was suggested that cellular recognition occurred through interaction of LcrV with the IFNγR-IFNγ complex." (PMID 21179438, 2010).
multiple system atrophy (2 papers, 2022 to 2024). Multiple system atrophy (MSA) is a neurodegenerative disorder characterized by autonomic failure (cardiovascular and/or urinary), parkinsonism, cerebellar impairment and corticospinal signs with a median survival of 6-9 years. "As interferon-stimulated genes, metallothioneins may combine with Interferon-gamma to upregulate microglia genes, a mechanism observed in multiple system atrophy." (PMID 36414996, 2022).
muscle atrophy (2 papers, 2017 to 2024). The loss of muscle tissue due to inactivity or disease. "Muscle atrophy is strongly linked to an increase in the generation of inflammation-inducing cytokines, including TNF-α (tumor necrosis factor-alpha), IL-1 (interleukin-1), IL-6 (interleukin-6), and IFN-γ (interferon-gamma)." (PMID 38732255, 2024). "Muscle atrophy as a result of chronic inflammation is associated with increased proinflammatory cytokine production, such as tumour necrosis factor alpha (TNF-α), interleukin 1 (IL-1), interleukin 6 (IL-6), and interferon gamma (IFN-γ; 59)." (PMID 28690764, 2017).
nasal natural killer/T-cell lymphoma (2 papers, 2023 to 2024). "For example, in nasal natural killer/T-cell lymphoma (NKTCL), which is commonly linked to Epstein–Barr virus (EBV), miR-142-3p is downregulated and IFNγ production is inhibited, thereby promoting lymphoma transformation with increased oncogenic BCL6 and IL1A cytokine expression." (PMID 38201290, 2023).
oligoarticular JIA (2 papers, 2019 to 2020). "Children with oligoarticular JIA have polarized synovial fluid monocytes of a specific M1(IFNγ)/M2(IL-4)-like pattern." (PMID 32787920, 2020).
oral candidiasis (2 papers, 2022 to 2024). Infection of the mucosal lining of the mouth with the fungus Candida albicans. "The study aimed to correlate serum interleukin 10 (IL-10) and interferon-gamma cytokines (IFN-γ) with oral candidiasis in T2DM." (PMID 36443718, 2022).
oral disease (2 papers, 2017). "Due to poor response of the other HPV-associated lesions to topical antiviral therapy, interferon-gamma (IFN-γ) treatment was initiated, producing resolution of the oral disease." (PMID 28603521, 2017).
oropharyngeal cancer (2 papers, 2015 to 2021). Carcinoma, predominantly squamous cell, arising from the epithelial cells of the oropharynx. "Another clinical study of AXAL in previously untreated, surgically resectable, stage II–IV oropharyngeal cancer found increased interferon gamma (IFN-g), tumor necrosis factor alpha (TNF-a), and tumor-infiltrating T cells after receiving the vaccine before and after surgery (NCT02002182)." (PMID 35008197, 2021).
otitis (2 papers, 2018 to 2025). "It has been postulated that OM susceptibility is due to impaired T cell-mediated immunity, with one study demonstrating reduced IFNγ+ memory CD4+ T cells in PBMC from otitis-prone children following challenge with recombinant NTHi antigens (but not SEB)." (PMID 29621281, 2018). "Otitis-prone children had more circulating IFNγ-producing NK cells (p<0.05) and more IFNγ-producing CD4+ (p<0.01) or CD8+ T-cells (p<0.05) than healthy controls." (PMID 29621281, 2018). "PBMC from children with CSLD have been found to produce less IL-6 and IFNγ in response to live NTHi challenge than healthy controls, but this was not apparent in the otitis-prone children in our study." (PMID 29621281, 2018). "Whereas the PBMC IFNγ responses to SEB in otitis-prone children was similar regardless of age, p = 0.797." (PMID 29621281, 2018). "The otitis-prone children ≤12 months of age (n = 6) had a higher IFNγ response to SEB than the age-matched controls (n = 14), 78pg/mL versus 15pg/mL, p = 0.05, demonstrating that PBMC from the otitis-prone children under ≤12 months of age in our study were capable of an IFNγ response." (PMID 29621281, 2018).
panic disorder (2 papers, 2020 to 2022). An anxiety disorder characterized by multiple unexpected panic attacks with persistent concern of recurring attacks. "In particular, patients with panic disorder (PD) present an inflammatory response due to elevated levels of pro‐inflammatory cytokines, such as interferon gamma (IFN‐γ), tumor necrosis factor alpha (TNF‐α), interleukin (IL) 6, and IL‐1β." (PMID 35588458, 2022).
pneumonic plague (2 papers, 2012 to 2013). A plague in which the bacteria have infected the lungs. "Indeed, it was previously shown that injection of IFNγ and TNFα protects mice against Y. pestis infection and that neutralization of these cytokines abrogates vaccine-induced protection against pneumonic plague." (PMID 22348169, 2012).
Pneumovirus Infections (2 papers, 2009 to 2016). Infections with viruses of the genus PNEUMOVIRUS, family PARAMYXOVIRIDAE. "Increased myeloid production was shown to be mediated by IFNγ during acute infection by the bacterium Ehrlichia muris and by TNFα and IFNγ during pneumovirus infection." (PMID 27335321, 2016). "Although first identified as a component of the antiviral response to Sindbis virus, the role of the Th1 cytokine, interferon-γ (IFNγ) in pneumovirus infection remains uncertain." (PMID 19298652, 2009). "Our data suggest that that IFNγ and CCL3 signaling pathways, both crucial features of the response to pneumovirus infection, interact in a hierarchical fashion, as IFNγ does not elicit neutrophil recruitment on its own, but is crucial for CCL3 to function effectively." (PMID 19298652, 2009).
pyoderma gangrenosum (2 papers, 2025). An idiopathic, rapidly evolving, and severely debilitating disease occurring most commonly in association with chronic ulcerative colitis. "Tan and Tolkachjov (2024) reported that pyoderma gangrenosum lesions exhibit elevated levels of proinflammatory molecules, including various cytokines, interleukins, JAK-1, JAK-2, JAK-3, and interferon gamma." (PMID 40353091, 2025).
pyometra (2 papers, 2016 to 2025). "The lack of transcription of IFNγ in normal diestrus and pyometra uteri is in accordance with the results of endometrial transcription and serum levels of IFNγ found in pyometra cases." (PMID 27829462, 2016).
radiculopathy (2 papers, 2020 to 2022). Disease involving a spinal nerve root (see spinal nerve roots) which may result from compression related to intervertebral disk displacement; spinal cord injuries; spinal diseases; and other conditions. "Likewise, elevated levels of pro‐inflammatory cytokines such as interleukin (IL)‐1b, IL‐6, IL‐8, IL‐17, tumour necrosis factor alpha (TNFα) and interferon gamma (IFNg) have been found in blood and disc tissue obtained during surgery in humans as well as in animal models of radiculopathy." (PMID 35357731, 2022).
Rb (2 papers, 2019 to 2021). "Encounter with any of the 3 retinoblastoma cell lines induced IFNG and IL2 release from CD171-specific CAR-T cells but not mock-transduced T cells used as negative controls." (PMID 31500597, 2019).
reactive arthritis (2 papers, 2017 to 2024). Reactive arthritis (ReA) is an autoimmune disorder belonging to the group of seronegative spondyloarthropathies and is characterized by the classic triad of arthritis, urethritis and conjunctivitis. "The authors demonstrated that PPI usage was independent of a single nucleotide polymorphism (SNP) in interferon gamma (IFN-γ) in cases with Campylobacter and NTS infections and the development of reactive arthritis." (PMID 27965105, 2017).
rectal tumor (2 papers, 2021 to 2022). "Lymphocytes in 3 (#8, #9 and #14) of 4 lymph nodes co-cultured with rectal tumor cells showed positive results in an IFNγ ELISPOT assay." (PMID 35606862, 2022).
scrapie (2 papers, 2021 to 2023). A fatal disease of the nervous system in sheep and goats, characterized by pruritus, debility, and locomotor incoordination. "Regarding molecular expression, strikingly, we found a significant increase in the quantity of IFNγ mRNA by RT-qPCR in a specific area (Fc) of clinically treated sheep, and these results could be reflecting the microglial expansion observed in previous studies in natural scrapie." (PMID 33540568, 2021).
Senile plaques (2 papers, 2014 to 2021). Senile plaques are extracellular deposits of amyloid in the gray matter of the brain. "IL1A, IL1B, IL2, IL8, IFNγ, and TNFα have been found to be associated with senile plaques." (PMID 25197660, 2014).
testicular germ cell tumours (2 papers, 2003 to 2007). "We recently reported that testicular germ cell tumours (TGCT) express a functional form of the proinflammatory cytokine interferon-gamma (IFNγ)." (PMID 12942126, 2003).
testicular tumour (2 papers, 2003 to 2019). "Based on this background, we next asked whether TGCT-derived IFNγ influences the proliferation and/or apoptosis of the testicular tumour cells in an autocrine manner." (PMID 12942126, 2003).
Trichiasis (2 papers, 2017 to 2019). Inversion and rubbing of the eyelashes against the globe of the eye. "In peripheral blood from adults with trichiasis and controls that were stimulated ex-vivo with C. trachomatis antigens, NK cells and to a lesser extent CD8+ T cells were the major sources of IFNγ with <50% of the IFNγ produced by CD4+ T cells." (PMID 28966918, 2017).
uterine fibroids (2 papers, 2023 to 2025). "Human uterine leiomyoma (HuLM) cells responded more to leptin treatment compared to myometrium cells with increased secretion of inflammatory factors: IFNγ, IL-6, IL-8, MCP-1, GM-CSF, and TNF-a." (PMID 36771423, 2023).
ventricular dilation (2 papers, 2008 to 2022). "This study has shown that irrespective of the underlying aetiology, early indications for HPHC (derived from concurring ventriculomegaly and macrocephaly) are accompanied by pro-inflammatory cytokine activation (IL-18 and IFNγ) with highest IL18 concentrations in post-hemorrhagic HPHC." (PMID 19117508, 2008). "In neonatal HPHC characterized by progressive ventriculomegaly and increased head circumference > P75, and control patients, this study aimed to determine and compare CSF IL18, IFNγ and sFasL concentrations." (PMID 19117508, 2008).
abdominal abscess (1 paper, 2010). An abscess located in the abdominal cavity, i.e., the cavity between the diaphragm above and the pelvis below. "In the absence of TLR-2, ZPS-induced secretion of interferon gamma (IFNγ) by CD4 T cells and intra-abdominal abscess inductions were significantly reduced." (PMID 21234388, 2010).
Acanthamoeba infection (1 paper, 2025). "Several cytokines, such as interferon-gamma (IFN-γ), interleukin (IL)-4, IL-10, IL-17A, IL-17F, and IL-22, are rapidly produced and secreted in response to Acanthamoeba infection." (PMID 40109888, 2025).
acute laryngitis (1 paper, 2024). An acute inflammatory process affecting the larynx. "Multivariate logistic regression analysis showed that the tumor necrosis factor-alpha, interleukin (IL)-4, IL-6, IL-17, and interferon-gamma levels were risk factors for acute laryngitis complicated by laryngeal obstruction." (PMID 39969319, 2024).
adrenal carcinoma (1 paper, 2015). A carcinoma involving a adrenal gland. "Our microarray analysis in SW13 adrenal carcinoma cells did not reveal a prominent effect on immune genes until we treated with IFNγ, but we wondered if there might be a more prominent effect on basal expression of immune pathways in other cancer types." (PMID 26030458, 2015).
anal carcinoma (1 paper, 2021). "Interferon-gamma (IFN-γ) is a key arbiter in inducing the anti-tumour effects of radiation, and given the role of MHC class I and PD-L1 in determining treatment response and outcomes for anal cancer patients, their expression was assessed by IHC and flow cytometry." (PMID 34663790, 2021).